APOA1 (apolipoprotein A1)
Diseases named in the same sentence as APOA1 in open-access papers (continued):
Sharing a sentence is not in itself a finding about the gene and the disease.
Cognitive impairment (24 papers, 2012 to 2025). Abnormal cognition is characterized by deficits in thinking, reasoning, or remembering. "In multivariable-adjusted regression model, serum apolipoprotein A1 was independently associated with cognitive impairment in patients with T2DM (OR = 5.201, p = 0.024)." (PMID 38167163, 2024). "The association between serum ApoA1 or ApoB levels and cognitive impairment in patients with schizophrenia were regulated by the existence of ApoE rs429358 polymorphism." (PMID 34135129, 2021). "The serum concentration of cognitive impairment-linked biomarkers revealed an increase in apolipoprotein A1 (ApoA1) and Transthyretin (TTR) levels in the experimental group at 16 weeks." (PMID 34720860, 2021). "After adjusting for other factors, ApoA1 and ApoA2 were found to be associated with cognitive impairment." (PMID 26682220, 2015). "The limitations of the study are as follows: First, the causality between serum apolipoprotein A1 and cognitive impairment in patients with T2DM is unclear due to the cross-sectional design of this study, therefore, the interpretation of the results should be done with caution." (PMID 38167163, 2024). "APOA1 gene polymorphism has also been related to cognitive impairment." (PMID 36927447, 2023). "However, similar findings among APOE ε4 carriers with subjective cognitive impairment and higher CSF ApoA1 have been associated with an increased risk of clinical progression toward AD." (PMID 36927447, 2023). "Similarly, a study reported that ApoA1 level was independently associated with cognitive impairment as shown by the Mini Mental Status Examination (MMSE) in elderly men." (PMID 34135129, 2021). "We hypothesized that the ApoE polymorphism rs429358 would lead to the changes in ApoA1 and ApoB levels, thereby playing a role in cognitive impairment in schizophrenia." (PMID 34135129, 2021). "The finding of increased oxidation of ApoA1 is in line with recent reports highlighting that ApoA1 dysfunction may be linked to increased susceptibility to cognitive impairment." (PMID 26752631, 2016). "However, after adjusting for age, AS levels, BMI, and comorbidity numbers, only ApoA1 and ApoA2 were found to be possible risk factors of cognitive impairment in older men." (PMID 26682220, 2015). "Therefore, APOA1 gene polymorphism might foresee future cognitive impairment." (PMID 40137124, 2025). "Our study initiated to explore the relationship between blood lipids and cognitive impairment in patients with T2DM, we found that increased serum apolipoprotein A1 levels were significantly associated with cognitive impairment in patients with T2DM." (PMID 38167163, 2024). "Second, owing to the cross-sectional study design, the causality between ApoE rs429358, ApoA1 and ApoB levels, and cognition impairment in patients with schizophrenia was not directly revealed." (PMID 34135129, 2021). "As the elevated ApoB/ApoA1 ratio may lead to large RN volume, the increased lesion volume may contribute to cognition impairment." (PMID 32017458, 2020). "Subjects with older age, a lower level of ApoA1, and a higher level of ApoA2 might have more possibilities of undergoing cognitive impairment." (PMID 26682220, 2015). "Furthermore, including lipid profile as covariates did not affect the ability of ApoA1, ApoA2 and ApoH levels and ApoB/ApoA1 ratio to predict cognitive impairment." (PMID 22701550, 2012). "The mechanism of this association between apolipoprotein A1 and cognitive impairment may not be completely clear in T2DM, however, some emerging evidences may contribute to explain this underlying mechanism." (PMID 38167163, 2024). "Serum apolipoprotein A1 is associated with cognitive impairment in patients with T2DM, but not TC, TG, HDL-C, LDL-C, and apolipoprotein B, indicating that increased serum apolipoprotein A1 may be a risk factor of cognitive impairment in patients with T2DM." (PMID 38167163, 2024).
Cognitive impairment (continued). "However, the association between ApoA1 and cognitive impairment was not significant, which is consistent with the result of a randomized, double-blind, placebo-controlled clinical trial." (PMID 36506447, 2022). "Therefore, we conducted this study to explore the relationship between cognitive impairment and ApoA1 and ApoB levels in patients with schizophrenia, because it may be altered by the ApoE polymorphism rs429358." (PMID 34135129, 2021). "The result presented that ApoA1 and ApoA2 might actually have impacts on cognitive impairment." (PMID 26682220, 2015). "ApoA1, ApoH and ApoJ may be potential clinical biomarkers for cognitive impairment." (PMID 22701550, 2012). "Serum apolipoprotein A1 levels were found to be significantly increased in T2DM patients with cognitive impairment compared with T2DM patients without cognitive impairment (p = 0.017)." (PMID 38167163, 2024). "Serum apolipoprotein A1 levels were significantly increased in T2DM patients with cognitive impairment compared with T2DM patients without cognitive impairment (p = 0.017)." (PMID 38167163, 2024). "Our study further identifies ApoA1 as a novel negative predictor for cognitive impairment in CSVD, aligning with emerging research in neurodegenerative conditions." (PMID 38952470, 2024). "In support of this hypothesis, our unpublished data reveal that plasma levels of ApoA1 are downregulated in both MDD patients and depressive-like mice and that plasma ApoA1 levels are negatively correlated with the severity of depressive symptoms and cognitive impairment in MDD patients." (PMID 35479414, 2022).
chronic kidney disease (22 papers, 2007 to 2025). Impairment of the renal function secondary to chronic kidney damage persisting for three or more months. "APOB and APOA1 levels are predictors of cardiovascular events and all-cause mortality in patients with chronic kidney disease." (PMID 40787622, 2025). "More importantly, this ratio has a stronger association with CHD incidence in chronic kidney disease (CKD) patients compared with ApoB/ApoA1." (PMID 30593279, 2018). "Meanwhile, Daud et al27 found that administering 180 mg of TRF daily for 16 weeks to individuals with end-stage renal disease led to a significant increase in apolipoprotein A1 (ApoA1) and HDL-C, as well as a significant decrease in plasma triacylglycerol (TG), LDL-C, and cholesteryl-ester transfer." (PMID 38916919, 2025). "APOA4 is elevated in patients with chronic kidney disease, and APOA1 in diabetic rat bladders." (PMID 25915536, 2015). "Apolipoprotein A1, the key protein component of HDL, and apolipoprotein B, the major protein component of VLDL and LDL, are closely linked to chronic kidney disease (CKD)." (PMID 39860649, 2025).
endothelial dysfunction (22 papers, 2010 to 2026). In vascular diseases, endothelial dysfunction is a systemic pathological state of the endothelium (the inner lining of blood vessels) and can be broadly defined as an imbalance between vasodilating and vasoconstricting substances produced by (or acting on) the endothelium. "The increase in urinary albumin, fetuin, and apolipoprotein A1 may all be consequences of a similar underlying mechanism: endothelial dysfunction resulting in a loss of functionality of the glomerular filtration barrier." (PMID 39335603, 2024). "Downregulation of APOA1 is in accordance with data showing that ApoA-1 is less prevalent in PH, which contributes to oxidative stress and endothelial dysfunction." (PMID 36902298, 2023).
liver fibrosis (22 papers, 2010 to 2025). "This comprehensive approach will facilitate validating the potential of TG/APOA1 as a reliable marker in assessing the risk of advanced liver fibrosis in MAFLD." (PMID 39764250, 2024). "Therefore, in the large cohorts of patients followed by FibroTest for a risk of liver fibrosis (named serum-cohorts) we aim to compare the daily value of serum apolipoprotein-A1, of the ongoing year 2020 to previous years “Covid-19 Free”." (PMID 33216772, 2020). "This sensitive, preclinical decline—occurring before conventional liver function abnormalities—underscores apolipoprotein A1 (Apo-A1)’s distinct utility as an early warning biomarker for hepatic fibrosis and its potential role in disease stratification." (PMID 40809427, 2025). "From the multitude of lipidic profile parameters, we chose only the total cholesterol, triglycerides, and APOA1, as these are relevant for the evaluation of liver fibrosis using a FibroMax test." (PMID 36140194, 2022). "The induction of liver fibrosis by CCl4 led to a significant (P < 0.05) increase in the serum levels of alpha-2-macroglobulin and a significant (P < 0.05) decrease in APOA1 in serum after 5 and 9 weeks of CCl4 treatment compared to the control group." (PMID 35881285, 2022). "Here, we preliminarily validated the relationship between plasma ApoA1, ApoA4, as well as haptoglobin and liver fibrosis to judge which plasma biomarker is better for the early detection of liver fibrosis." (PMID 29179490, 2017). "Sensitivities and specificities of panel markers (ApoA4+HPG+ ApoA1) for early liver fibrosis detection can be greatly improved." (PMID 29179490, 2017). "Of these targeted proteins, HPT and ApoA1 also scored in the FibroTest, indicating that proteome analysis is a feasible tool for diagnosis of liver fibrosis." (PMID 29179490, 2017). "The relation of HDL mediated lipid transport with liver fibrosis was well-known and noninvasive FibroTest involving serum apolipoprotein-A1 have already been in clinical use for diagnosis of liver fibrosis." (PMID 28439208, 2016). "Indirect markers of liver fibrosis include specific transaminases or molecules such as α2-macroglobulin, apolipoprotein A1, haptoglobin, γ-glutamyl transpeptidase (GGT) and bilirubin, which are components of a common assay of liver fibrosis known as Fibrotest." (PMID 27458976, 2016). "This profile was never observed before in our prospective data on apolipoprotein-A1 from and since the first cohort of alcoholic liver disease in 1982 nor in patients at risk of liver fibrosis followed with FibroTest, which include apolipoprotein-A1 in its components." (PMID 33216772, 2020). "In liver fibrosis, decreased serum ApoA1 is observed without hepatic insufficiency, the ApoA1 being trapped by the collagenization of the endothelial cells before advanced fibrosis and before the hepatic insufficiency." (PMID 35327501, 2022). "The univariate prognostic value of apolipoprotein-A1 was confirmed but to our knowledge, it was the first time that its prognostic value persisted after adjustment by age, a marker of acute inflammation (haptoglobin), a sensitive marker of liver injury (GGT), and a marker of liver fibrosis (A2M)." (PMID 33216772, 2020).
Cirrhosis (21 papers, 2009 to 2025). A chronic disorder of the liver in which liver tissue becomes scarred and is partially replaced by regenerative nodules and fibrotic tissue resulting in loss of liver function. "ApoA1 is the major protein component of high-density lipoprotein in the plasma, and a decrease of ApoA1 has been found in the plasma of patients with hepatic cirrhosis." (PMID 29179490, 2017). "Centrality and cluster screening identified hub genes, including APOE, TTR, CLU, and APOA1 in cirrhosis." (PMID 28224023, 2016). "In fact, a reduction of ApoA1 in the serum of patients with cirrhosis has remained a constitutive part of combined peptide panels used to predict fibrosis for a number of years." (PMID 19656391, 2009). "In addition Pro-ApoA1, spot 3, was markedly present in all individuals with cirrhosis and HCC relative to only trace amounts in simple steatosis patients and cirrhotic patients without HCC." (PMID 19656391, 2009). "According to our previous network analysis of differentially expressed proteins in cirrhosis serum based on literatures, APOA1 and APOE have been introduced as key proteins (hub) in cirrhosis." (PMID 33585012, 2020). "The finding pointed to the significant role of APOA1 and CLU as the common two biomarker in development of cirrhosis and HCC diseases." (PMID 28224023, 2016). "Apolipoprotein A1 (ApoA-1), the major component of HDL was demonstrated to be decreased in patients with cirrhosis, and also after liver transplantation when methylprednisolone given intraoperatively may have contributed to repressing the HPA axis." (PMID 30483216, 2018).
dyslipidaemia (21 papers, 2007 to 2025). "Polymorphisms of the APOA1 gene were identified with a varied prevalence/incidence of the development of dyslipidaemia following the initiation of AA treatment." (PMID 41017289, 2025). "Two significant gene polymorphisms of APOA1, 75G/A and 83C/T, were identified as having association in the development of dyslipidaemia in patients treated with AAs." (PMID 41017289, 2025). "Additionally, gene polymorphisms affecting the APOA1 protein, a protein involved in cholesterol re‐uptake by the liver, have been shown to affect the severity of dyslipidaemia experienced by adult patients with schizophrenia treated with AAs." (PMID 41017289, 2025). "ApoA1, eGFR, haemoglobin (Hb), and albumin (Alb) were lower in the dyslipidaemia group than in the non-dyslipidaemia group (P<0.05, for each)." (PMID 33112407, 2020). "Confirming the recent data on the association between systemic inflammation and dyslipidaemia in OSA, lipid markers except for ApoA1 and LPA correlated with CRP." (PMID 30712133, 2019). "Decreased values of apoA-1 potentiated the impact of apoB at all levels of apoB (on average across apoB range: 40% increase in HR for MACE and 72% increase in HR for non-fatal MI), indicating that the apoB/apoA-1 ratio covers a broader range of persons with dyslipidaemia at risk than apoB alone." (PMID 34851955, 2021). "T2DM is associated with dyslipidaemia that is characterized by raised triglyceride, and low HDL cholesterol and therefore, it is tempting to speculate such confounding factors could mask the influence of apoA1 genotyping on lipoprotein phenotype." (PMID 17683612, 2007). "For example, the association of the inflammatory biomarkers MIF and WBCs with AA‐induced dyslipidaemia, as well as the metabolic proteins asprosin, IGFBP‐2, and APOA1 highlight potential areas for further research." (PMID 41017289, 2025).
Hyperglycemia (21 papers, 2013 to 2025). An increased concentration of glucose in the blood. "Studies have confirmed the positive correlation between LDL-C and hyperglycemia, whereas HDL-C and apoA1 were associated reversely with hyperglycemia and increased HbA1c." (PMID 38786962, 2024). "In contrast, hyperglycemia-induced glycation of apolipoprotein A1 inhibits its ability to activate lecithin-cholesterol acyltransferase, resulting in a 40% reduction in HDL cholesterol efflux efficiency in diabetic models." (PMID 40483478, 2025). "Previous studies demonstrated that glucosamine could attenuate the vessel injury induced by hyperglycemia, promote apolipoprotein A1 expression and impair hepatic apolipoprotein B100 (apoB100) assembly and secretion." (PMID 26377577, 2015). "T2DM hyperglycemia leads to alterations in lipid metabolism, including enhanced HDL clearance, reduced apoA-1 transcription, and accelerated HDL glycation." (PMID 41245406, 2025).
rheumatoid arthritis (21 papers, 2004 to 2025). A chronic, systemic autoimmune disorder characterized by inflammation in the synovial membranes and articular surfaces. "A number of clinical prospective studies have shown that the Apo B/ApoA1 ratio is the risk factor for cardiovascular, osteoarthritis, rheumatoid arthritis, and metabolic syndrome disease." (PMID 34325707, 2021). "In patients with rheumatoid arthritis anti-apoA-1 IgG positivity was 17% and was associated with a higher incidence of major cardiovascular events." (PMID 29423541, 2018). "Furthermore, previous studies suggested that ApoA1 was associated with cardiovascular events in rheumatoid arthritis patients and CAD patients who underwent PCI." (PMID 32178685, 2020). "In rheumatoid arthritis anti-apoA-1 IgG improves the Framingham 10-year cardiovascular (CV) risk score." (PMID 29423541, 2018). "In rheumatoid arthritis and acute chest pain patients, anti-apoA-1 IgG was shown to be a promising biomarker providing significant incremental prognostic information to clinical scores, such as FRS or NSTEMI-TIMI score." (PMID 23258951, 2012). "Importantly, in a previous study done in the setting of another chronic inflammatory condition, rheumatoid arthritis, anti-apoA-1 antibodies were found to be an independent predictor of the presence of CVD." (PMID 34888742, 2022). "In inflammatory diseases such as rheumatoid arthritis (RA), elevated IL-6 levels are allied with decreased HDL-C and HDL-associated protein apoA-1." (PMID 37627620, 2023).
Abdominal obesity (20 papers, 2006 to 2024). Excessive fat around the stomach and abdomen. "Considering the central obesity indicators (waist circumference, hip circumference, waist-to-hip ratio) may have a positive or reverse causal relationship with the ApoB/ApoA1 ratio." (PMID 38310324, 2024). "As is evident from our data, there is a strong relationship between leptin, adiponectin, and abdominal obesity with increased CVD risk, as assessed by the apoB/apoA1 ratio." (PMID 16606459, 2006). "Our observation of a weak trend between the apoB/apoA-1 ratio and BC severity may reflect characteristics of the MetS such as abdominal obesity playing a role in BC development – however, experimental evidence is needed to support this hypothesis." (PMID 28376727, 2017). "People with central obesity were mainly women and had a worst cardiovascular risk profile than those without central obesity; indeed, they had higher values of glucose, HbA1c, LDL-cholesterol, apoB, systolic and diastolic blood pressure, and lower values of HDL-cholesterol and apoA1." (PMID 24788805, 2014). "In conclusion, women with PCOS and abdominal obesity (waist circumference⩾98 cm) had an altered metabolic profile in terms of HDL subclasses, total choline, albumin, apolipoprotein A1 and Apo B/Apo A1 ratio." (PMID 28546543, 2017).
systemic lupus erythematosus (20 papers, 2010 to 2025). An autoimmune multi-organ disease typically associated with vasculopathy and autoantibody production. "Elevated anti-apoA1 antibody titers are correlated with an increase in Systemic Lupus Erythematosus Disease Activity Index (SLEDAI) and are inversely proportional to PON1 activity." (PMID 39574464, 2024). "We therefore bred a lupus prone-mouse model (Nba2.Yaa mice) with Apoe−/− mice resulting in Apoe−/−Nba2.Yaa mice spontaneously producing anti-apoA-1 IgG antibodies." (PMID 33110193, 2020). "The present study showed lower expression of apolipoprotein A1 in lupus patients as compared to healthy controls." (PMID 22901283, 2012). "However, follow up of disease activity over 3-7 years (mean=4.9 years) revealed that the baseline ApoB:ApoA1 ratio correlated positively with average longitudinal SLEDAI-2000 score and negatively with longitudinal Lupus Low Disease Activity State (LLDAS)." (PMID 33640328, 2021). "Finally, baseline ApoB:ApoA1 ratio correlated positively with SLE disease activity index (r=0.43, p=0.0009) and negatively with Lupus Low Disease Activity State (r=-0.43, p=0.0009) over 5-year follow-up." (PMID 33640328, 2021).